TNF (tumor necrosis factor)
Diseases named in the same sentence as TNF in open-access papers (continued):
Sharing a sentence is not in itself a finding about the gene and the disease.
tumor (continued). "While a variable capacity to secrete IL-6, IL-1β and TNF-α is shared by differentially polarized macrophages, an IL-12 low/IL-10 high phenotype is the hallmark of M2 macrophages, which are known to promote tumor growth." (PMID 29454317, 2018). "Moreover, a link between high levels of TNF-α and increased risk of tumor formation and development has been described in vivo." (PMID 30591049, 2018). "Results indicated that blocking TNF may reduce tumor growth, which is associated with reduced tumor dissemination, angiogenesis, and infiltration with myeloid cells." (PMID 29593717, 2018). "TNF-α was originally discovered as a serum factor causing necrosis of tumor cells." (PMID 29751615, 2018). "Inflammatory cytokines (including tumor necrosis factor (TNF), Interleukins (IL) and chemokines, etc.)and immune cells (including tumor-associated macrophages and tumor infiltrating lymphocytes, etc.)in tumor microenvironment contribute to tumor growth, metastasis and immunosuppression." (PMID 29291712, 2018). "Furthermore, as an endogenous tumor-promoting factor, TNF-α can also cause epithelial mesenchymal transition (EMT) in several types of cancer cells." (PMID 29467927, 2018). "To address this issue, we analyzed the ability of IFN-γ and TNF-α to modulate the expression of a panel of genes encoding a variety of factors known to be produced by tumor cells and of potential relevance in tumor progression and inhibition of immune responses." (PMID 29896191, 2018). "IgE treatment was associated with elevated serum concentrations of TNFα, a mediator previously linked with IgE‐mediated antitumour and antiparasitic functions, alongside evidence of substantially elevated tumoural immune cell infiltration and immunological pathway activation in tumour‐bearing lungs." (PMID 29654623, 2018). "Notably, ST2 deficiency resulted in lower IFN-γ, TNF-α, IL-10, and IL-17 production in tumor samples." (PMID 30112116, 2018). "Also consistent with its effects in Myc-CaP tumors, CP1 increased PD-1 on CD8 TILs, decreased the percentage of Treg TILs, and caused decreased VEGF and increased MIP-2, IL-17, and TNFα within the tumor microenvironment." (PMID 29686284, 2018). "In mouse models of cancers, reduced tumor growth in mice treated by anti-TNF drugs or in TNFR2 knockout mice was associated with decreased numbers of MDSCs suggesting that TNF increases survival, recruitment, or function of MDSCs that suppress antitumor immunity." (PMID 29593717, 2018). "Therefore, understanding the mechanism underlying the resistance of tumour cells to TNF‐α killing and finding available approaches to overcome the drug resistance are urgently required." (PMID 29632814, 2018). "Importantly IFN-γ and TNF-α are also potent inducers of the expression of the immune checkpoint ligands PD-L1 and PD-L2 in macrophages/dendritic cells, tumor cells and tumor-associated endothelial cells." (PMID 30364222, 2018). "However, dysregulated TNF-α signaling is also associated with the promotion of tumor cell growth via the mediation of epithelial-mesenchymal transition (EMT)." (PMID 30631327, 2018). "The association between TNF-α-308 G>A polymorphism and neutrophils may be unrelated to neoplasm location (colon or rectum), although further confirmation is necessary." (PMID 28575042, 2017). "Neutrophils have been considered to be the primary source of circulating VEGF, which play a critical role in tumor-associated angiogenesis through producing many inflammatory cytokines such as tumor necrosis factor, interleukin 1, and providing a favorable micro-environment for tumor." (PMID 28187430, 2017). "Moreover, the tumor-promoting activity of TNF-α was confirmed by two-stage carcinogenesis experiments on the skin of TNF-α deficient (TNF-α−/−) 129/Svj mice and TNF-α+/+ CD-1 mice treated with DMBA plus okadaic acid and with DMBA plus TPA." (PMID 28124725, 2017).
tumor (continued). "As inflammation microenvironment is strongly linked with tumor progression, we then investigated whether pro-inflammatory factor TNF-α could promote SCC-9 × HUVEC fusion." (PMID 28112190, 2017). "Moreover, a high level of TNF-α in combination with IL-6 in ascites’ fluid and tumor tissue of OC patients is associated with tumor progression and resistance to chemotherapy concomitant with shortened progression-free survival." (PMID 28725636, 2017). "Irradiation caused higher expression of both IL-6 and TNF-α in tumour cells." (PMID 29070894, 2017). "We suggest that secretion of this and other factors by the tumor activates a cascade of transcription factors and enzymes associated with the induction of TNF-α and TGF-β signaling pathways, which, in turn, are prominent inducers of EMT, and are strongly activated in the adjacent endothelium." (PMID 29057876, 2017). "In the tumor tissue, TNFα was associated with tumor type and gender (p = 0.049 and p = 0.002)." (PMID 28537901, 2017). "Furthermore, the production of TNF-α by malignant cells in mice has been shown to affect tumor-associated myeloid cell activity, in turn affecting tumor growth." (PMID 28915246, 2017). "Indeed, systemic treatment using recombinant TNF-α (rTNF-α) caused CT26 tumor regression in wild-type mice with a macroscopic developmental profile similar to previously tested more complex therapies like bacteria (SL7207) or the upstream stimulant LPS." (PMID 28445131, 2017). "Interestingly, TNF-α was overexpressed in Stage III and IV tumors, suggesting that high TNF-α expression in tumor cells can be associated with advanced stages of carcinogenesis." (PMID 28492497, 2017). "This study indicates the therapeutic efficacy and safety of TNFα expressing bacteria in vivo, highlighting the potential of non-pathogenic bacteria as a platform for restricting the activity of highly potent cancer agents to tumours." (PMID 28662099, 2017). "Moreover, the levels of mRNA of ESM1 were found to be highly regulated by inflammatory cytokines, such as tumor necrosis factor α and interleukin 1, and be linked with tumor growth and angiogenic process during tumor progression." (PMID 28108731, 2017). "On one hand, Nur77-deficient inflammatory cells secrete TNF-α to drive tumor cells to undergo EMT." (PMID 28170411, 2017). "Notably, TNF-α -308 GA and AA genotypes showed strong association with distant tumor metastasis (OR = 2.911; 95% CI: 1.697–4.992; P = 0.00017)." (PMID 28575042, 2017). "This might have triggered TNFα production from tumor associated macrophages (TAM) with a subsequent stimulation of tumor growth." (PMID 28160574, 2017). "Clinicopathological features of CRC patients classified by tumor site and TNF-α -308 polymorphism." (PMID 28575042, 2017). "Examples of key players of cancer-related inflammation (CRI) include tumor-infiltrating lymphocytes, tumour-associated macrophages (TAMs), the secretion of cytokines such as TNF, IL-1, IL-6, and chemokines such as CCL2 and CXCL8, in addition to the occurrence of tissue remodeling and angiogenesis." (PMID 27555866, 2016). "Variations for sensitive parameters could cause a significant increase of the critical dose of TNF-α to enlarge the cells survival region, ultimately facilitating oncogenesis and tumour progression." (PMID 27129147, 2016). "The gadd-TNF-α system also causes a cytotoxic response that is effective in killing tumor cells." (PMID 27875983, 2016). "We therefore evaluated whether the anti-tumor activity of LFs was associated with its anti-inflammatory properties through inhibiting pro-inflammatory cytokines and mediators (IL-1β, IL-6, TNF-α, iNOS and Cox-2)." (PMID 27563884, 2016). "The question is whether administration of PGRN or a derivative confers a higher risk of iatrogenic induced neoplasms than administration of conventional TNF blockers." (PMID 27428882, 2016).
tumor (continued). "TNFα, an inflammatory cytokine causes hyperactivation of the NFκB signaling pathway which results in activation of pro-survival pathway and promotes aggressive phenotype in tumor cells." (PMID 26940200, 2016). "TNF-α is a key mediator of inflammatory reactions, and it can cause tumor cell necrosis." (PMID 27324794, 2016). "g., IL6 and TNF) that kill cancer cells; however, MΦ2 macrophages the predominant tumor associated macrophages in late stage cancers release anti-inflammatory IL-10, and a variety of growth factors (VEGF, FGF etc), that promote growth and vascularization of the cancer mass." (PMID 27231721, 2016). "Progression in tumor stage and size are associated with high levels of IL-1β, IL-6 and TNF-α." (PMID 27507058, 2016). "It is well known that TAMs (tumor-associate macrophages) have a reduced capacity to produce anti-tumor molecules, such as NO, TNFα, ROS, and IL-1; instead, TAMs support tumor survival, growth and metastasis and play a pivotal role in tumor angiogenesis and immune evasion." (PMID 27020049, 2016). "In a simplified view, tumor infiltrating monocytes, macrophages and Th17 lymphocytes produce cytokines like IL-1, IL-6, IL-17, IL-23 and TNFα, which signal to exacerbate tumor-associated inflammation and activate survival and proliferation machinery in cancer cells." (PMID 31051015, 2016). "Second, tumor cells themselves and tumor-associated leukocytes could produce various inflammatory cytokines, such as tumor necrosis factor-alpha, interleukin-6, and vascular endothelial growth factor." (PMID 27342313, 2016). "In vivo, two distinct and successive effects of TNF-α on tumour-associated vasculature are known." (PMID 25810699, 2015). "In addition, IL-16 can activate the secretion of tumor-associated inflammatory cytokines, such as TNF-α, IL-1β, IL-6, and IL-15, all of which are major factors involved in tumorigenesis." (PMID 25954818, 2015). "Furthermore, disruption of heat shock protein 90 (Hsp90) function by geldanamycin causes RIPK1 degradation, which sensitizes tumor cells to TNF-induced apoptosis." (PMID 25790448, 2015). "Intriguingly, TNFα neutralization could prevent IHC loss due to one tumour’s secretions (VS8) and prevent OHC loss (VS6) in another case." (PMID 26690506, 2015). "It is also important to stress that TNFα can be secreted locally in tumors essentially by macrophages, resulting in a receptor-mediated activation of NF-κB that promotes tumor growth during cancer-associated chronic inflammation (for details, see reference Muntané, 2011)." (PMID 26528183, 2015). "Interestingly, patients with TNBC and the TNF-α-308A allele had an increased risk of distant tumour metastasis." (PMID 26165253, 2015). "This association might be mediated by the constitutively higher expression of tmTNF-α and/or sTNF-α in patients with the TNF-α-308A allele, promoting tumour growth through metastasis." (PMID 26165253, 2015). "Balkwill's group implicated TNF-α in the tumor-macrophage cross-talk." (PMID 26684869, 2015). "Furthermore, previous studies on mechanisms by which tumor cells induce T cell apoptosis implicated tumor associated Fas ligand (FasL) and other tumor necrosis factor (TNF)-related ligands in the process." (PMID 26226135, 2015). "Repressed TNF-α and IL-6 inhibit tumor growth in experimental models of colitis-associated cancer." (PMID 24766737, 2014). "This angiogenic function might be due to the ability of TNF-α to cause differentiation of myeloid progenitor cells into endothelial cells within the tumor microenvironment." (PMID 24466321, 2014). "As a pro-inflammatory cytokine from macrophages and tumor microenvironment, TNFα has been implicated in cancer promotion and progression, possibly by mediating epithelial-mesenchymal transition required for tumor invasion and angiogenesis, and has been investigated as a target for cancer therapy." (PMID 24473087, 2014).
tumor (continued). "TNF-α activates associated cell signaling pathways through the activation of transcription factors and related genes, consequently affecting the activity of tumor cells, promoting tumor cell proliferation." (PMID 24676340, 2014). "A study has shown that tumour growth caused by tobacco smoke was mediated by IL-6 and TNF-α." (PMID 26316944, 2014). "Thus, tumor vessel damage and increased drug penetration are thought to be crucial mechanisms underlying how TNF-α synergizes with chemotherapeutic drugs." (PMID 24466321, 2014). "In RCC TNFα is produced by tumor-associated macrophages (TAM)." (PMID 24885059, 2014). "In 1975, Carswell found a factor that can rapidly cause hemorrhaging and tumor necrosis, named TNF." (PMID 24676340, 2014). "TNF-α also inhibits tumor-induced vascularization by damaging the tumor-associated vasculature." (PMID 25548907, 2014). "However, to our knowledge, the present study is the first to demonstrate a similar effect using the tumor-homing peptide RGD-4C coupled to the recombinant mutated human TNF-α (RGD-rmhTNF-α)." (PMID 24466321, 2014). "Moreover, tumor-associated macrophages, which are refractory to LPS exhibit strong overexpression of p50 and fail to induce TNFα expression despite normal levels of p65/RelA and its ability to re-localize to the nucleus upon LPS treatment." (PMID 24843008, 2014). "Interestingly, the two main cellular sources of TNFα are tumor-associated macrophages (TAM) and the BC cells themselves, highlighting the role of inflammatory macrophages in BC." (PMID 25360510, 2014). "Since NT5E and DCLB2 inversely affect cell proliferation and associate with patients’ outcome, the interplay of TNF-α with PPARγ revealed by our approach could represent a pivotal relay-point in determining tumor progression towards a more aggressive behavior." (PMID 24133572, 2013). "Since TNF-α has a strong antitumoral action, the up-regulated expression of TNF-α post REV-A infection may correlate with tumor caused by REV." (PMID 24358317, 2013). "In addition, High TNFα expression is strongly associated with tumor recurrence in CRC patients with positive lymph node metastase." (PMID 23431386, 2013). "TNF-α is associated with cell-cycle progression, tumor growth, and oxidative stress, stimulating the expression of Transforming Growth Factor alpha (TGF-α) in mouse hepatocytes and the formation of 8-oxodeoxyguanosine, a critical biomarker of oxidative stress and carcinogenesis." (PMID 23533994, 2013). "In addition to its tumor killing properties, TNF-α has also been identified as the major cause of SE-induced toxicity in mice." (PMID 23964349, 2013). "Furthermore, due to the discordance between HPV serological and tumor status, we determined the tumor HPV16 status for SCCOP patients to further explore the association between these TNF-α promoter variants and susceptibility to HPV-associated SCCOP." (PMID 23870134, 2013). "In addition, blocking TNF-α skews tumor-associated MRC1+Tie2+ TAMs from a pro-angiogenic phenotype to a pro-inflammatory/angiostatic phenotype, indicated by the upregulation of IL-12." (PMID 24314323, 2013). "In this respect, the combined use of a low dose of sTNF with a TNFR2-selective TNF variant may optimize therapeutic effects on tumor vasculature and minimize toxicity." (PMID 23840967, 2013). "The resulting tumor-associated macrophages may secrete TNFα, which induces or up-regulates the secretion of several promalignancy factors from the tumor cells such as matrix metalloproteinases." (PMID 22408433, 2012). "Thus, transfer of Cl-IB-MECA-treated CD8+ T cells which are able to produce TNF-α, was associated with a significant recruitment of LCs into the tumor tissue." (PMID 23028986, 2012). "All of these processes are also implicated in tumour-associated chronic inflammation; therefore, it is conceivable that blockade of TNF could be efficacious against early-stage PCa." (PMID 23326670, 2012).
tumor (continued). "In support of this hypothesis, we demonstrate that the disruption of stromal TNF-α signaling suppresses inflammatory gene expression in tumor-associated endothelial cells and significantly impairs tumor growth." (PMID 23056240, 2012). "However, TNFα has been shown to inhibit tumor angiogenesis, synergize with radiation therapy, and a spike in serum TNFα was associated with one documented case of abscopal tumor regression." (PMID 22761754, 2012). "In addition to promoting carcinogenesis, tumor associated macrophages (TAMs) and their released factors (e.g. IL-1, TNF-α) have long been known to support all steps of invasion and metastasis." (PMID 21880137, 2011). "Tumor associated macrophages and other immune cells are the major source of TNFα." (PMID 21479220, 2011). "PAX3- and PAX7-FKHR gene fusion, mutations in the von Hippel Lindau tumor suppressor gene, hypoxia in the tumor microenvironment, NF-κB, and inflammatory cytokines such as vascular endothelial growth factor and tumor necrosis factor alpha, have all been implicated in CXCR4 overexpression." (PMID 21880153, 2011). "The weighted mortality hazard ratios in the anti-TNF cohort were as follows: all-cause 0.86 (95% confidence interval [95% CI] 0.64–1.16), circulatory disease 0.73 (95% CI 0.44–1.23), neoplasm 0.65 (95% CI 0.39–1.09), and respiratory disease 0.81 (95% CI 0.36–1.83)." (PMID 20662063, 2010). "These led to our speculation that one of the underlying mechanisms of TNF-α in tumor metastasis may be related to the upregulation of chemokines/chemokine receptors." (PMID 20699000, 2010). "Macrophages' involvement in the carcinogenesis and tumor invasion and metastasis generally is blamed to motivate TAMs (Tumor associated macrophages), a major source of TNF-α in tumor microenvironment, to release a variety of growth factors, cytokines, and inflammatory mediators." (PMID 20699000, 2010). "As an approach towards modelling the cytokine environment in tumor tissues we here address effects of TNFα, a prominent inflammatory cytokine produced by tumor infiltrating macrophages, on laminin-332 expression in Smad4-positive and Smad4-deficient tumor cells." (PMID 20307265, 2010). "Loss of Smad4 may lead to uncoupled induction of laminin-γ2 in response to TNFα and may therefore represent one of the mechanisms which underlie accumulation of laminin-γ2 at the invasive margin of a tumor." (PMID 20307265, 2010). "TNF-α one of major cytokines produced by tumor-associated macrophages, is known to activate NF-κB." (PMID 18335034, 2008). "A recent report has shown TNF-α plus interferon γ to induce selective loss of myosin in murine myotubes, and this was also found in tibialis anterior muscle from the hind limb of cachectic mice bearing the colon 26 tumours." (PMID 16052213, 2005). "Moreover, TNF-α is one of the angiogenic factors associated with tumour-induced neovascularisation and gefitinib has been shown to inhibit EGFR-mediated migration and tube-like formation of human microvascular endothelial cells." (PMID 15841081, 2005). "Previous studies led to the hypothesis that the use of TNF-α in isolated limb perfusion causes specific destruction of tumour endothelial cells and thereby induces an increased permeability of tumour vasculature." (PMID 12610519, 2003). "Of the 54 patients with the TNF+488A polymorphism, nine (16.7%) presented with a G1 tumour." (PMID 12966432, 2003). "On the other hand, Jun can stimulate apoptosis in a range of cancer cell types and play a tumour-suppressing role, for example, in a manner inversely related to JunD or by transcriptional regulation of senescence- and inflammation-associated genes including IL-1β, TNFα, CCL3 and CCL8." (PMID 39859271, 2025). "In addition, the damage-associated molecular patterns (DAMPs) released by tumor cells after being killed by particles can activate macrophages and neutrophils, leading to abnormal upregulation of inflammatory factors such as IL-1β, IL-6, and TNF-α." (PMID 40740952, 2025).